BRCA1 (BRCA1 DNA repair associated)
Diseases named in the same sentence as BRCA1 in open-access papers (continued):
Sharing a sentence is not in itself a finding about the gene and the disease.
cancer (continued). "This could be expected to be different if cancer predisposition genes such as BRCA1 or BRCA2 were included in the return of SFs, as in a recent paper from the BabySeq project, where the return of a genomic finding in children led to risk reducing surgeries in parents." (PMID 38740897, 2024). "Furthermore, being FHS7 positive was associated with a 3-fold increase in the risk of being BRCA1/2 positive for both sexes and a 44% increase in cancer risk among living female individuals, indicating that FHS7 is useful for indicating genetic risk even without counselor validation." (PMID 39320887, 2024). "The 313-SNP PRS was associated with both female and male BC risk in BRCA PV carriers, suggesting that risk profiling on the basis of PRS may provide a further individual cancer risk stratification for carriers of BRCA1/2 PVs, with implications for their clinical management." (PMID 38339330, 2024). "However, it remains unclear whether additional factors are required for fork recovery in BRCA1-deficient cancer cells." (PMID 38943334, 2024). "There are many polymorphisms in the BRCA1 gene, which may be associated with cancer susceptibility." (PMID 38892180, 2024). "While hCCAR2 deletion could compromise cancer cells’ invasive properties or resilience to various stresses, thus inducing cancer cell death, hCCAR2 deletion in an HR-deficient background (e.g., BRCA1/2 mutant) may confer a growth advantage on cancer cells by restoring genetic stability." (PMID 38172598, 2024). "In addition, germline genetic testing plays a crucial role in cancer treatment, as BRCA1/2 mutations are predictive of a positive response to PARP inhibitors and platinum-based chemotherapy, while mutations in mismatch repair genes suggest potential benefits from immune checkpoint inhibitors." (PMID 39684385, 2024). "Importantly, ATR inhibition abolishes the restored RAD51 foci and the loading of RAD51 to replication forks in BRCA1-deficient, PARPi-resistant cancer cells, supporting the idea that ATR inhibition disrupts a common RAD51-mediated mechanism driving PARPi resistance." (PMID 39007266, 2024). "Whilst accounting for a small proportion of cancer cases—0.1% of BC and around 1% of PCa—the risk for carriers to develop BC increases up to 1% and 7–8%, while for PCa it ranges to almost 4-fold increase and from 3 to 8.6-fold increase, for BRCA1 and BRCA2 mutations, respectively." (PMID 38203374, 2023). "In addition, similarly to PARP1 or DNA polymerase Polθ inhibitors that are used to treat HR-deficient cancers, the small molecule JE-RH-06 disrupts the interaction between the TLS polymerases REV1 and Polζ and shows preferential cytotoxicity in BRCA1-deficient cancer cells." (PMID 36749784, 2023). "These may include more intensive screening strategies, e.g., the combination of mammography and MRI and genetic counseling, which may help detect cancer’s onset at an earlier stage, delay the disease’s progression, and enhance the quality of life for BRCA1 variant carriers." (PMID 38201529, 2023).
cancer (continued). "Therefore, designing a strategy that confers a “BRCAness” phenotype in PDAC cancer cells might render PDAC patients with WT BRCA1/2 susceptible to PARP inhibition." (PMID 37415733, 2023). "Thus, our data suggest that a significant portion of patients with BRCA1 mutation-containing cancers might show a limited response to Polθi monotherapy." (PMID 38001070, 2023). "The rising interest in APE2 as a drug target for precision medicine in chemotherapy is largely due to the multiple reports of its SL with BRCA1- and BRCA2-deficient cell lines, suggesting that inhibiting APE2 may lead to the loss of viability in BRCA1/2-deficient cancer cells." (PMID 36755963, 2023). "Given that BRCA1/2 participates in cell division by regulating various molecular events during mitosis, mutations that cause functional transcriptional disruption of BRCA1/2 may lead to cancer development." (PMID 37351713, 2023). "Although this phenotype, broadly termed BRCAness, is most commonly associated with germline mutations in BRCA1/2, evidence from basic and clinical studies suggest that other genetic and epigenetic alterations may have similar effects on cancer risk, tumor molecular features, and drug sensitivity." (PMID 37291133, 2023). "However, BRCA1 CC domain missense mutations in patients with cancer are relatively uncommon." (PMID 38001070, 2023). "Therefore, exploring the causes of cancer caused by BRCA1/2 mutation from the perspective of mechanism is significantly helpful to evaluate the clinical risk of BRCA1/2 mutation carriers, and also helps to provide different immunotherapy programs for different mutation patients." (PMID 36765522, 2023). "Additionally, this may be a significant therapeutic strategy for cancer patients with BRCA1 mutations, especially for those who develop PARPi resistance." (PMID 37760968, 2023). "In addition, multigene panel testing using NGS (next generation sequencing) technology could identify up to 50% more individuals with cancer susceptibility gene mutations in comparison with testing only for BRCA1 and BRCA2." (PMID 36707770, 2023). "Importantly, these specific histone H1 variants are highly expressed in cancer cells, suggesting that the interaction between BRCA1 and H1.3, H1.5, and H1.2 might depend on expression levels of these specific replicative histone H1 variants." (PMID 37364916, 2023). "However, these BRCA1/2-deficient cancer cells have been able to develop tumors." (PMID 36613695, 2022). "Interestingly, these BRCA1-mutated cancer cells resist apoptosis and proliferate smoothly." (PMID 35517499, 2022). "In addition, we assess the WID-OC-index in normal fimbrial and high-grade serous tissue and cell lines, and in a large range of tissue samples, and find that the WID-OC-index is significantly associated with those tissues that show a high rate of BRCA-1/2 germline-mediated cancer formation." (PMID 35105887, 2022). "Herein, we review recent studies on the importance of G4s in the mutational landscapes of the cancer genome and in cell-type-specific transcriptional regulation, and summarize the evidence that the accumulation of unresolved G4s is responsible for tissue-specific tumorigenesis by BRCA1 deficiency." (PMID 35327946, 2022). "Therefore, the amplification of TRIP13 induces resistance to PARPi in BRCA1/2-mutated cancers." (PMID 36497275, 2022). "It remains unclear how BRCA1-associated mutational sigantures are generated in cancer." (PMID 35879372, 2022). "BRCA1 1100delAT and BRCA1 5589del8 were found to have a partial ancestral effect in the Han Chinese population and may be used as biomarkers to assess the risk of developing breast, ovarian, and other cancers in women." (PMID 36397405, 2022). "Thus, pyridostatin‐based drug combinations may represent a viable strategy for the treatment of BRCA1/2‐mutated cancer patients." (PMID 35107878, 2022).
cancer (continued). "However; despite being the earliest, most common and arguably most widely established paradigm of high penetrance cancer susceptibility, recent analyses suggest low ascertainment, with fewer than 3% of BRCA1/BRCA2 heterozygotes across Greater London identified." (PMID 35868849, 2022). "In addition, BRCA1/2-deficient cancer cells may develop PARPi resistance by protecting their replication forks; they achieve this by blocking the recruitment of nucleases, MRE11 or MUS81, to the stalled fork, thereby resulting in fork protection." (PMID 36499000, 2022). "Several structural variations are typical of BRCA1/2-deficient cancer genomes, including deletions up to 100 kb, unclustered tandem duplications of ∼10 kb associated with BRCA1 mutations, and deletions up to 1-10 kb in cancers are found in patients with BRCA2 mutations." (PMID 35783256, 2022). "In addition, cancer risk genes other than BRCA1 and BRCA2 cannot be overlooked, which may contribute to HBOC susceptibility." (PMID 36230639, 2022). "However, there has been controversy as to whether carriers of germline pathogenic variants (PVs) in BRCA1 and 2 (BRCA1/2) or other cancer susceptibility genes benefit from some chemotherapy drugs more than others." (PMID 35723570, 2022). "In patients with localized ER+/HER2- cancer associated with bulky node involvement after initial surgery, or treated with neoadjuvant chemotherapy, BRCA1/2 status genotyping should be implemented, so olaparib can be prescribed as an adjuvant treatment in patients carrying BRCA1/2 PV." (PMID 35158866, 2022). "However, haploinsufficiency may also promote the formation and progression of tumors, and the rate of biallelic inactivation of BRCA1 in pathogenic germline carriers is cancer type-specific." (PMID 35327946, 2022). "Indeed, patients carrying a germline BRCA1 variant can develop a sporadic tumor, independently of BRCA1 loss of function, highlighting the need to demonstrate the causal role of the variant in the cancer development." (PMID 35280729, 2022). "Thus, inhibiting Alt-NHEJ in HR-deficient BRCA1-mutant cancers leads to synthetic lethality." (PMID 36207426, 2022). "Moreover, given the differing cancer risk profiles between BRCA1 and BRCA2, it is unknown whether women’s reproductive decision-making differs between those harboring a BRCA1 vs. BRCA2 variant." (PMID 35326645, 2022). "To determine whether and how BRCA1 mutations influence the proteome, phosphoproteome and ubiquitinome within the cancer patient group we compared the changes in BRCA1mut (n = 5) and BRCA1wt (n = 5) cancer tissues." (PMID 35292711, 2022). "Thus, combined treatment of cell growth inhibitors and PARP inhibitors might efficiently kill BRCA1-deficient cancer cells." (PMID 35368664, 2022). "Therefore, we envision a scenario where the CtIP-BARD1 genetic interaction could potentially be exploited therapeutically for cancer treatment especially in the context of BRCA1-deficient cancers that develop therapy resistance." (PMID 35203293, 2022). "Future clinical trials using BRCA1/2 variant status or HRD status as an enrolment criterion may allow the indications of PARP inhibitors to be expanded beyond its current indications in BRCA1/2-associated cancer types." (PMID 36577523, 2022). "BRCA1 PVs were associated with male breast (RR = 4.30; 95% CI, 1.09 to 16.96), gallbladder (RR = 3.34; 95% CI, 1.34 to 8.28), pancreatic (RR = 2.36; 95% CI, 1.51 to 3.68), stomach (RR = 2.17; 95% CI, 1.25 to 3.77), and colorectal (RR = 1.48; 95% CI, 1.01 to 2.16) cancers." (PMID 35077220, 2022). "Given the high incidence of germline alteration (~12%) and important implications for family members who may be at risk of hereditary cancers, a positive BRCA1/2 tumour test should be followed up with germline testing and a referral to the genetics counsellors as needed." (PMID 36497408, 2022).
cancer (continued). "This tissue-specific tumorigenesis has been a critical question from the beginning of BRCA1 research, in that the mechanism underlying tissue-specificity of cancer-associated molecular alteration may also reveal tissue-specific therapeutic vulnerabilities and preventive strategies." (PMID 35327946, 2022). "However, HRD also occurs in tumors without germline BRCA1/2 mutations, indicating that the use of these therapies could be extended beyond germline BRCA1/2 mutated cancers." (PMID 35662281, 2022). "However, there is growing suspicion that distinct biological processes may also be at play, especially in cancers where BRCA1 deficiency is due to gene silencing through promoter methylation." (PMID 35857626, 2022). "In addition, TNBC accounts for more than 75% of cancers that arise in women with BRCA1 mutations." (PMID 36192752, 2022). "While researching independent evidence for the pathogenicity of BRCA1 c.5407-25T>A, we surveyed the ClinVar database for rare, intronic BRCA1 variants located beyond ±20 nucleotides, rationalizing that this resource would report variants with biologically meaningful associations with cancer risk." (PMID 35456503, 2022). "Thus, the BRCA1 RING domain could determine phenotypes associated with modulation of RNF168 activity in cancer." (PMID 34408138, 2021). "However, BRCA1 mutated cancers had higher expression compared to the BRCA2 mutant subset." (PMID 34465787, 2021). "It is well known, indeed, that hereditary cancers are generally characterized from an earlier age of onset of BC; therefore, the combination of early age of onset and positive BC family history represents a very strong risk factor and is generally associated with germline mutation in BRCA1 gene." (PMID 33691613, 2021). "Therefore, BRCA1-deficient cancer cells show high sensitivity to topoisomerase inhibitors." (PMID 33784323, 2021). "While a subset of these cancers classified as heterozygous BRCA1/2 loss may have inactivated the second allele by methylation, it is notable that environmental and endogenous genotoxins such as aldehydes have been shown to induce BRCA2 haploinsufficiency and consequent genome instability." (PMID 34877933, 2021). "However, screening BRCA1/2 also resulted in the discovery of thousands of generally rare missense substitutions, the influence of which on cancer risk is unknown." (PMID 34359619, 2021). "Indeed, inhibition of USP1-UAF1 by the small molecule ML323 destabilizes replication forks and decreases the viability of the BRCA1-deficient cells, suggesting that USP1 inhibitors may have potential therapeutic use in BRCA1-deficient cancers." (PMID 34359655, 2021). "Thus, increased ROS levels in basal-like subtypes of TNBCs may be associated with BRCA1 mutation/inactivation and may be essential for the survival of this type of cancer." (PMID 33498875, 2021). "Together these results suggest that globally expression variability associates with phenotypic features of BRCA1-associated cancer to a stronger degree than mean expression and at an individual gene level, associations may not be statistically significant if only mean expression level is examined." (PMID 34287743, 2021). "Heterozygous carriers of variants in a gene associated with autosomal recessive forms of FA are not at risk of FA, but may be at increased risk of breast, ovarian, and/or other cancers, if the monoallelic variants in question are in BRCA1, BRCA2, PALB2, BRIP1 or RAD51C." (PMID 34771713, 2021). "Finally, considering that RANK expression has been reported in a significant proportion of cancers arising in BRCA1 mutation carriers, it will also be interesting to study denosumab in the early stages of BRCA1-driven tumorigenesis and/or as add-on therapy to reduce the risk of contralateral BCa." (PMID 34440747, 2021).
cancer (continued). "Therefore, we speculate that the background BRCA1/2 mutational status in cancers may be similar, and the emergence of certain mutations in a cancer may be random, while the enrichment of the mutations may be cancer-specific." (PMID 33563323, 2021). "Next, to test whether CHORD is generalizable to all tissue types, we held out samples belonging to each cancer type from the training set (but grouped cancer types with few BRCA1/2 deficient samples), and trained random forests in the same manner as was done for CHORD." (PMID 33149131, 2020). "However, DNA fibre analysis showed, unlike effects observed in HR-deficient OVCAR8 RAD51C KO cells, forks stalled by hydroxyurea (HU) were not degraded in WEHICS62 cells, indicating fork protection, a mechanism associated with PARPi-resistance in BRCA1-deficient cancer cells." (PMID 32457376, 2020). "Furthermore, the reason why BRCA1/2 mutations are particularly associated with specific cancer types, such as breast, ovarian and PCa remains unknown." (PMID 31197228, 2020). "Thus, human mammary epithelial organoid cultures could be used to model tumorigenesis for cell-of-origin studies of BRCA1-associated BCs, and now make it feasible to directly examine the impact of cancer-associated alterations on luminal progenitor cells." (PMID 32249764, 2020). "Based on this analysis, we constructed evolution models for Brca1-deficient tumors, showing that tumors initiate from cells with SNVs affecting potential driver genes in premalignant stage and progress via CNVs acquired in chromosome regions with many cancer driver genes." (PMID 32978388, 2020). "The risk assessment of BRCA1/2 mutation carriers inheriting other RAD52 variants that disrupt the protein function may also identify other alleles that are associated with reduced cancer risk." (PMID 32255263, 2020). "Therefore, we investigated VD levels and actions in cancer free women with BRCA1 mutations." (PMID 33227068, 2020). "Besides, somatic mutations of BRCA1/2 (sBRCAm) have also been suggested in various cancer types." (PMID 32563252, 2020). "Thus, inhibition of DNA damage response (DDR) mechanisms, especially with PARP1 depletion in BRCA1/2‐deficient models, may decrease the survival of cancer cells and promote a more effective antitumour therapy." (PMID 32686903, 2020). "Based on these results, and previous mechanistic and epidemiological studies, we hypothesized that the positive association between cancers in young black patients and early-onset AD death could be, at least in part, explained by the BRCA1 deficiency in these individuals." (PMID 32224926, 2020). "Therefore, the identification of the BRCA1/2 gene mutations, the fast practice, and concluding of the gene analysis are highly important in planning the treatment and identifying the secondary cancer risk." (PMID 33488844, 2020). "Thus, in the absence of BRCA1, excessive RNF168 expression may drive BIR, and contribute to the mutational signatures observed in BRCA1-mutated cancers." (PMID 32182354, 2020). "This hypothesis and the possibly occurring psychological urge to fulfill family planning in a certain time in order to schedule risk-reducing surgery procedures contribute to the fact that fertility treatment and cancer risk is of particular interest for the subgroup of BRCA1/2 mutation carriers." (PMID 32719921, 2020). "Furthermore, RD‐N‐induced cell death was exacerbated in BRCA1‐deficient cancer cells." (PMID 30565390, 2019). "However, characterizing the point mutations associated with cancer in BRCA1 is challenging because the functional impact of most of them is still unknown." (PMID 31998812, 2019). "Despite being the national cancer institution, the territorial extension of the country (1,964 million km2) and other migratory, social and cultural phenomena, limit the generalisation that can be made of the distribution of the founder mutation 9–12 del BRCA1 in our population." (PMID 31545835, 2019).